SLC6A13 (solute carrier family 6 member 13)
Description:
Mediates sodium- and chloride-dependent transport of gamma-aminobutyric acid (GABA). Mediates transport of beta-alanine. Can also mediate transport of taurine and hypotaurine (By similarity).
Synonyms: GAT-2; GAT2; GAT3
Tractability: Small molecule: it belongs to a druggable protein family. Antibody: UniProt places it where antibodies can reach, with high confidence; its Gene Ontology location is reachable by antibodies, with high confidence; UniProt predicts a signal peptide or a membrane-spanning region. PROTAC: a small molecule that binds it is known.
Target class: SLC superfamily of solute carriers; SLC06 neurotransmitter transporter family; Electrochemical transporter; Transporter
Gene: Protein-coding gene on chromosome 12 (220,621 to 262,873, reverse strand). Ensembl gene ENSG00000010379.
Subcellular location: Cell membrane; Basolateral cell membrane
Subcellular location (Human Protein Atlas): Mitochondria; Cytosol; Nucleoli; Nucleoplasm
Pathways (Reactome):
Neuronal System: Reuptake of GABA
Transport of small molecules: SLC-mediated transport of neurotransmitters
Gene Ontology:
Molecular function: amino acid transmembrane transporter activity; amino acid:sodium symporter activity; gamma-aminobutyric acid:sodium:chloride symporter activity; monocarboxylic acid transmembrane transporter activity; creatine transmembrane transporter activity; gamma-aminobutyric acid transmembrane transporter activity; taurine:sodium symporter activity; transmembrane transporter activity
Biological process: amino acid import across plasma membrane; monocarboxylic acid transport; amino acid transport; creatine transmembrane transport; gamma-aminobutyric acid import; gamma-aminobutyric acid reuptake; neurotransmitter transport; sodium ion transmembrane transport; taurine transmembrane transport; transport across blood-brain barrier
Cellular component: extracellular exosome; mitochondrion; plasma membrane; basolateral plasma membrane; membrane; presynapse
Genetic constraint (gnomAD): Loss-of-function variants: 60 observed, 64.74 expected, observed/expected ratio (o/e) 0.93, 90% interval 0.75 to 1.15. The upper end of that interval is the gene's LOEUF score, 1.15, which puts it in group 5 of 6, group 1 being the genes least tolerant of losing a copy. Missense variants: 654 observed, 705.75 expected, observed/expected ratio (o/e) 0.93, 90% interval 0.87 to 0.99. Synonymous variants: 271 observed, 286.19 expected, observed/expected ratio (o/e) 0.95, 90% interval 0.86 to 1.05.
Homologues: Orthologues: chimpanzee SLC6A13 (99% identical), pig SLC6A13 (93% identical), dog SLC6A13 (93% identical), rat Slc6a13 (92% identical), mouse Slc6a13 (91% identical), guinea pig SLC6A13 (89% identical), zebrafish SLC6A13 (73% identical). Paralogues in human: SLC6A12 (71% identical), SLC6A11 (68% identical), SLC6A6 (61% identical), SLC6A8 (54% identical), SLC6A7 (46% identical), SLC6A5 (45% identical), SLC6A2 (43% identical), SLC6A9 (43% identical), SLC6A4 (42% identical), SLC6A3 (41% identical), SLC6A14 (40% identical), and 6 more.
Diseases named in the same sentence as SLC6A13 in open-access papers:
SLC6A13 is named in the same sentence as 23 diseases in open-access papers, as found by Europe PMC text mining. Sharing a sentence is not in itself a finding about the gene and the disease. The quoted sentences say what the papers report.
autism (1 paper, 2020). Persistent deficits in social interaction and communication and interaction as well as a markedly restricted repertoire of activity and interest as well as repetitive patterns of behavior. "Seven genes were in common between the syndromic and non-syndromic autism-related genes and our dataset and included Avpr1a and the glutamate transporter (Slc6a13)." (PMID 32365465, 2020).
chronic kidney disease (1 paper, 2015). Impairment of the renal function secondary to chronic kidney damage persisting for three or more months. "The newly discovered loci also include variants previously linked to chronic kidney disease (CPS1, SLC6A13), pulmonary hypertension (CPS1), and ischemic stroke (XYLB)." (PMID 26352407, 2015).
Hypoglycemia (1 paper, 2016). A decreased concentration of glucose in the blood. "Moreover, we were able to point out several glycoproteins (Fibulin1, Versican, Fibromodulin) linked to the extracellular matrix (ECM), many crystallins and few solute carriers (Slc26a4, Slc6a13) whose expression was modified by hypoglycemia." (PMID 26918849, 2016).
liver cancer (1 paper, 2024). An epithelial or non-epithelial malignant neoplasm that arises from the liver. "Study on inflammasome activation had shown that overexpression of SLC6A13 in liver cancer cell lines regulates the expression of key components of the inflammasome." (PMID 38780447, 2024). "The results of our bioinformatics in our study on TCGA-LIHC, GSE14520, and GSE67764 datasets showed that SLC6A13 expression was continuously downregulated in liver cancer samples." (PMID 38780447, 2024). "We analyzed the differentially expressed genes (DEGs) in the Cancer Genome Atlas-Liver Hepatocellular Carcinoma (TCGA-LIHC) database, as well as in the GSE14520 and GSE67764 datasets, to identify the expression changes of SLC6A13 in liver cancer." (PMID 38780447, 2024).
Type 2 Diabetes (1 paper, 2021). "Missense mutations in the SLC6A12 and SLC6A13 genes are significantly associated with an increased incidence of type 2 diabetes (T2D)." (PMID 34192533, 2021). "We used the Accelerating Medicines Partnership Type 2 Diabetes Knowledge Portal to understand the effect of missense mutations in genes encoding the hepatic GABA transporters (SLC6A6, SLC6A8, SLC6A12, and SLC6A13)." (PMID 34192533, 2021).
tumour (3 papers, 2020 to 2024). "Expression analysis further showed that the expression of SLC6A13 was downregulated in tumor samples compared with normal samples in the TCGA-LIHC dataset (P ═ 1.1e−05), GSE145290 dataset, and GSE67764 dataset." (PMID 38780447, 2024). "The purpose of this research was to clarify the function of achaete-scute family bHLH transcription factor 1 (ASCL1) and solute carrier family 6 member 13 (SLC6A13) in influencing tumor cell behavior, inflammatory responses, and the regulation of inflammasomes." (PMID 38780447, 2024). "The research also showed that ASCL1, which had a positive correlation with SLC6A13, controls the production of this protein and suppresses the growth, migration, and invasion of HCC cells, hence functioning as a tumor suppressor." (PMID 38780447, 2024). "This suggested that SLC6A13 may play an important role in regulating key enzymes related to amino acid metabolism, thereby affecting the metabolic status of HCC cells and the tumor microenvironment." (PMID 38780447, 2024). "Likewise, the following marker genes were selected for analysis in PF tumours: LAMA2, ALDH1L1, SLC6A13, IGSF1, and CXorf67 for PFA; and NELL2, DNAH1, CEP83, C9orf72, and NXNL2 for PFB tumours." (PMID 34314101, 2021).
cancer (1 paper, 2024). A tumor composed of atypical neoplastic, often pleomorphic cells that invade other tissues. "Furthermore, UALCAN database analysis showed that SLC6A13 expression was not affected by nodal metastasis status and individual cancer stages." (PMID 38780447, 2024).
infection (1 paper, 2016). The state of being infected such as from the introduction of a foreign agent such as serum, vaccine, antigenic substance or organism. "The epithelial marker genes, including γ-GT1, claudin-2, and SLC6A13, were downregulated by TGF-β1 stimulation for 48 h, and then began to increase significantly from 12 h to 18 h after Ad-HNF1B infection." (PMID 27196561, 2016).
neurological disorders (1 paper, 2025). "The dysregulation of the SLC6A13 function has been associated with various neurological disorders." (PMID 40002984, 2025).
SLC6A13 also shares sentences with these, for which no sentence is quoted: alcohol use disorders (1 paper); Alzheimer disease (1); anxiety disorder (1); hepatocellular carcinoma (1); iminoglycinuria (1); Intellectual disability (1); ischemic stroke (1); manic depression (1); memory impairment (1); neutropenia (1); Parkinson's (1); pulmonary hypertension (1); schizophrenia (1); tuberous sclerosis (1).